CLDN1 (claudin 1)
Diseases named in the same sentence as CLDN1 in open-access papers (continued):
Sharing a sentence is not in itself a finding about the gene and the disease.
lung carcinoma (continued). "Therefore, in lung cancers, high claudin-1 expression is more likely to be observed in tumors with a squamous cell phenotype than in tumors with other cell phenotypes, whereas tumors with adenocarcinoma components are likely to lose claudin-1 expression." (PMID 34354941, 2021). "In addition, CLDN1 was highly expressed in cell lines derived from human lung cancer tissues." (PMID 32824620, 2020). "CD44 overexpression significantly increased migration and invasion abilities of lung cancer cells through CD44-induced ERK phosphorylation, ZEB1 upregulation, and Claudin-1 downregulation." (PMID 34439211, 2021). "In CL1-5 lung cancer cells, cell migration activity was inhibited by over-expression of CLDN-1 and restored by CLDN-1 knockdown in addition to cell invasion ability." (PMID 31952355, 2020). "An experiment in human lung cancer cell lines, observed that TNFα induced the expression of CLDN-1, and knockdown of CLDN-1 blocked 75% of TNFα-induced gene expression." (PMID 31952355, 2020). "The basal levels of CLDN1 in lung cancer cell lines were detected by RT-qPCR and showed that Hop62 is high CLDN1-expressing cells, and CL1-5 is low CLDN1-expressing cells." (PMID 32754286, 2020). "CLDN1 is a tight junction protein reported in colorectal, oral, ovarian, and lung cancers, but no cancer treatments, including CAR-T cell therapy, targeting it have yet been developed." (PMID 40076777, 2025). "Notably, genes such as CLDN1 and CLDN18 control cell adhesion and tight junctions and were found in both gastric and lung cancer." (PMID 40565055, 2025). "Claudin-1 (CLDN1), a tight junctional protein, is highly expressed in lung cancer cells and may contribute to chemoresistance." (PMID 32824620, 2020). "Indeed, overexpression of claudin-1 was shown to induce EMT through activation of slug and zeb1 in human liver cells, and to mediate TNF-alpha induced cell migration in human lung carcinoma." (PMID 25171249, 2014).
gastric cancer (35 papers, 2011 to 2026). A primary or metastatic malignant neoplasm involving the stomach. "One study demonstrated that the localization and correlation of CLDN-1 expression are linked with anoikis resistance in gastric cancer through mediating membrane β-catenin expression and by inducing cell aggregation and inhibiting apoptosis cascade." (PMID 31952355, 2020). "The invasion of gastric adenocarcinoma cells is associated with the levels of CLDN-1 expression as CLDN-1 is found to be upregulated in gastric carcinoma and participates in the metastatic behavior of these cancer cells." (PMID 31952355, 2020). "Gastric cancer, the second leading cause of cancer death worldwide, the heterogeneous expression of CLDNs subtypes such as claudin-1, -3, -4, -6, -7, -9 and -18 have been found." (PMID 25544763, 2015). "Additionally, CLDN1 has been implicated in modulating signaling pathways, such as Wnt/β-catenin, further contributing to intestinal-type gastric cancer progression and the spread of malignant cells." (PMID 41399659, 2026). "Claudin 1 is overexpressed in gastric cancer and is associated with tumor invasion and metastasis." (PMID 40687428, 2025). "Thus we considered that TJ protein CLDN1 is an anti-anoikis protein in gastric cancer and deficiency of CLDN1 expression suppressed cell aggregation and cell survival when deprived of cell-matrix adhesion." (PMID 25544763, 2015). "CLDN1 was highly up-regulated in gastric cancer, and CLDN1 expression was independently associated with a poor post-operative prognosis, and may have important prognostic value." (PMID 24321518, 2013). "For example, claudin-1 is associated with colon cancer prognosis, claudin-18 is related to gastric cancer (GC) prognosis, and claudin-10 is relevant to hepatocellular carcinoma prognosis." (PMID 38511141, 2024). "These discrepancies suggest that the prognostic or metastatic value of CLDN1 expression in gastric cancer is context-dependent and warrants further clarification through large-scale clinical studies and mechanistic research." (PMID 40687428, 2025). "Functional studies have demonstrated that silencing CLDN1 in gastric cancer cells leads to a marked reduction in proliferation, migration, and invasive capacity." (PMID 40687428, 2025). "DNA promoter hypermethylation is associated with downregulation of CLDN1 and CLDN7 in breast cancer and CLDN11 in gastric cancer cells." (PMID 38731853, 2024). "CLDN1 expression was also suppressed by the transcription of the tumor suppressor factor RUNX3 in gastric cancer." (PMID 38731853, 2024). "This is further confirmed by the positive correlation of CLDN1 expression levels with β-catenin levels in gastric cancer." (PMID 36672179, 2023). "A potential role for β-catenin has been described in CLDN1-regulated anoikis resistance in gastric cancer cells, with β-catenin overexpression also reactivating Akt and Src signaling." (PMID 36672179, 2023). "Western blot analysis was performed to detect the expression of claudin 1, c-Myc, cyclin D1, Bcl-2, and caspase-3 proteins in gastric cancer cell lines after treatment with miR-155-5p and Res." (PMID 35789645, 2022). "This demonstrated that β-elemene can inhibit the invasive and migratory ability of gastric cancer cells by reducing claudin-1 expression." (PMID 36362132, 2022). "In this study, the investigators used RNA sequencing to examine differentially expressed genes in gastric cancer cells after treatment with β-elemene and found claudin-1 expression to be reduced significantly." (PMID 36362132, 2022). "Elevated expression of CLDN1 in cancer cells results in increased proliferation, migration, invasion in gastric cancer cells, but also protects them against apoptosis." (PMID 34822542, 2021). "Use of monoclonal antibodies for claudin targeting led to very promising in vivo results; in particular with anti-Cldn18 or -Cldn1 antibodies for treatment of gastric cancer or HCV infections, respectively." (PMID 31561440, 2019).
gastric cancer (continued). "CLDN1, 2, 6, 9, 16, and 19 were found to be of significance in gastric cancer in the tight junction family, and CLDN6 expression was the highest." (PMID 31827075, 2019). "In the current study, we demonstrated that knockdown of CLDN1 expression in gastric cancer cells inhibited tumor growth and metastasis in vitro and in vivo by inducing cell anoikis." (PMID 25544763, 2015). "What’s more, our team has been worked on some of the differential genes such as PHF10, CEACAM6, SFRP1, SOX11, CLDN1 to investigate their expression and functions in gastric cancer and the results perfect proved our microarray data." (PMID 25928635, 2015). "Here, we both down and up regulated CLDN1 expression in gastric cancer cells to elucidate its role in gastric carcinogenesis and tumor progression." (PMID 25544763, 2015). "To reinforce its oncogenic functions, we up-regulated CLDN1 expression in two gastric cancer cell lines of AGS and NCI-N87." (PMID 25544763, 2015). "By using CLDN1-KD gastric cancer cell lines as a model, we found that CLDN1-KD cells exhibited decreased cell migration and invasion in vitro." (PMID 25544763, 2015). "In the present study, we showed that knockdown or overexpress of CLDN1 induced variation of membrane β-catenin in gastric cancer cells." (PMID 25544763, 2015). "Collectively, these results indicated that CLDN1 played a role in gastric cancer tumorigenesis and metastasis." (PMID 25544763, 2015). "To further explore the role of β-catenin in the CLDN1 regulated anoikis in gastric cancer, we transfected β-catenin into HS-746T/CLDN1-KD cells using lentiviral vector." (PMID 25544763, 2015). "CLDN1 was over-expressed in gastric cancer tissues, its expression was correlated with tumor invasiveness and metastasis, and was a prognostic factor of poor outcome." (PMID 25544763, 2015). "Claudin-1 (CLDN1) is overexpressed in gastric cancer and correlated with tumor invasion, metastasis and poor outcome." (PMID 25544763, 2015). "After establish other two gastric cancer cell lines with CLDN1 overexpression, we obtained opposite results to the CLDN1-KD cells." (PMID 25544763, 2015). "CLDN1 has been identified within the nucleus of gastric cancer AGS cells in vitro, suggesting a regulatory role of CLDN1 on cell proliferation, migration and invasiveness at a nuclear level." (PMID 24321518, 2013). "In our study, CLDN1 was not only highly up-regulated in the gastric cancer samples, but CLDN1 expression was also independently associated with a very poor post-operative prognosis." (PMID 24321518, 2013). "The expression of claudin-1, -3 and -4 is higher in the intestinal type of gastric adenocarcinoma than in the diffuse type of gastric cancer." (PMID 24009024, 2013). "There is evidence that several of the claudins, CLDN1 included, show increasing levels as gastric epithelium progresses to intestinal metaplasia and early gastric carcinoma." (PMID 24321518, 2013). "Recent studies comparing gastric cancer and normal tissue have identified a number of genetic markers, including diagnostic markers [NF2, INHBA, SFRP4], prognostic markers [CD9, CDH17, PDCD6], and gastric cancer-associated genes [MUC13, CLDN1, Ki67 and CD34]." (PMID 22133303, 2011). "Claudin-1 has been shown to be highly expressed in gastric cancer tissues, particularly in intestinal-type tumors and CLDN1 overexpression was positively associated with more advanced TNM stages, the presence of lymph node metastasis and well-differentiated tumors." (PMID 41399659, 2026). "Conversely, its expression is downregulated in esophageal cancer (which is associated with a reduced immune response), gastric cancer (where it inhibits gastric cancer cell proliferation and promotes cell apoptosis), and ovarian cancer (where it down-regulates Claudin-1), among others." (PMID 39963112, 2025). "Furthermore, CLDN1-mediated anoikis resistance and Scr involvement were also described in gastric cancer." (PMID 36672179, 2023).
gastric cancer (continued). "Hence, β-elemene inhibits the metastasis of gastric cancer by modulating the FAK/claudin-1 signaling pathway." (PMID 36362132, 2022). "Claudin-1 is oncogenic in gastric cancer, and its malignant potential may be attributed in part to the regulation of anoikis by mediating membrane β-catenin-regulated cell-to-cell adhesion and cell survival." (PMID 36010553, 2022). "The authors also observed that the levels of CLDN-1 expression in gastric cancer tissues decreased from well to moderate to poorly differentiated tumors, suggesting that reduced CLDN-1 expression is an adverse prognostic factor predicting a lower survival rate." (PMID 31952355, 2020). "For CLDN1, its overexpression in gastric cancer is related with tumor invasion and metastasis." (PMID 25544763, 2015). "As 3D culture is an in vitro experiment reflecting the anti-anoikis ability of cancer cells, and anti-anoikis ability is related to the tumorigenesis which has been confirmed in this study, we proposed that CLDN1 had an anti-anoikis potential in gastric cancer." (PMID 25544763, 2015). "Here we further detected that membrane β-catenin could also be regulated by CLDN1, and CLDN1 regulated β-catenin expression may be a key pathway in the process of gastric cancer cell anoikis." (PMID 25544763, 2015). "Consistently, knockdown of CLDN1 in gastric cancer cells inhibited cell invasive ability." (PMID 25544763, 2015). "Given that CLDN1 is markedly up-regulated in gastric cancer tissus and cell lines, we hypothesized that CLDN1 may function as an oncogene." (PMID 25544763, 2015). "Taken together, our findings predict that the TJ protein CLDN1 may have a notable impact on the tumorigenic and metastatic capacities of human gastric cancer through maintenance of cell anoikis resistance." (PMID 25544763, 2015). "Taken together, these findings suggest that CLDN1 is oncogenic in gastric cancer and its malignant potential may be attributed in part to regulation of anoikis, by mediating membrane β-catenin-regulated cell-cell adhesion and cell survival." (PMID 25544763, 2015). "These opposite performance to the CLDN1-KD cells reinforce that CLDN1 might initiate gastric cancer generation and metastasis by maintaining anoikis resistance." (PMID 25544763, 2015). "We previously showed that the expression of CLDN1 was correlated with β-catenin expression in gastric cancer tissues, and CLDN1 expression could be regulated by β-catenin." (PMID 25544763, 2015). "IL-8 and CLDN1 may represent central links between the gene response seen in acute H. pylori infection of gastric epithelial cells, and ultimately gastric cancer." (PMID 24321518, 2013). "Thus, it would be of interest to compare the cell surface presence of CLDN18.2 (via antibodies) and (via YFP-cCPE) that of cCPE-receptor claudins indicated to be expressed in gastric cancer (CLDN1 to −4, −6, −7) in parental tumor tissue as well as the respective organoids." (PMID 37514167, 2023). "For example, claudin-1, which is highly expressed in the intestinal type of gastric cancer, is correlated with tumor invasion and migration and poor prognosis and overexpression of claudin-1 may promote the proliferation and migration of gastric cancer cells." (PMID 28350854, 2017). "In the gastric cancer dataset, three genes—FOXS1, PGF, and CLDN1 —were commonly identified by both explainability methods and the manuscript, further validating their relevance." (PMID 40565055, 2025). "BIRC5, CLDN1, DDX58, IL18, NPC2, NUSAP1, and PHC3 were found to have higher expression in gastric cancer tissues compared to normal tissues, and their expression was also elevated in various other cancer types." (PMID 40393971, 2025). "Of note, claudin-1 overexpression in the presence of an FAK inhibitor restores the invasive and migratory activity of gastric cancer cells." (PMID 36362132, 2022).
gastric cancer (continued). "In gastric cancer cell lines, BGC823 and SGC7901, β-elemene was found to inhibit peritoneal metastasis by modulating the focal adhesion kinase (FAK)/Claudin-1 signaling pathway, including downregulated FAK phosphorylation and Claudin-1 expression." (PMID 33801899, 2021). "Of the three claudins we identified to interact with an HIF-1 network, CLDN1 and CLDN4 were previously reported as upregulated in gastric cancer progression, while CLDN18 was downregulated." (PMID 29050243, 2017). "For instance, the transcription factor Cdx2 can enhance the expression of claudin-3 and -4 in gastric cancer cells, and the transcription factor RUNX3 can enhance the expression of claudin-1 by binding to its promoter region." (PMID 28350854, 2017). "However, the role and detailed mechanism of CLDN1 in gastric cancer are still unknown." (PMID 25544763, 2015). "Only three, CLDN7, CLDN1 and DPT, of these genes are significantly differentiated in all grades or stages of gastric cancer." (PMID 21445269, 2011). "For comparison, with CLDN1, also expressed in the healthy stomach and in gastric cancer, no clear and discrete colocalization was observed." (PMID 37514167, 2023). "Interestingly, we also found that the CLDN1-KD only impaired the gastric cancer cell growth in 3D culture, but not in monolayer culture." (PMID 25544763, 2015). "Although there are several papers to support an oncogenic role of CLDN1 in gastric cancer, two studies nevertheless showed reduced CLDN1 staining in metastatic compared to non-metastatic gastric cancer, and increased tumorgenicity in CLDN1 negative gastric epithelial cells, contrasting our findings." (PMID 24321518, 2013).
lung adenocarcinoma (33 papers, 2010 to 2025). A carcinoma that arises from the lung and is characterized by the presence of malignant glandular epithelial cells. "CLDN1 is also implicated as a tumour suppressor in lung adenocarcinoma, prostate and oestrogen receptor-positive breast cancer." (PMID 39367275, 2024). "Claudin-1 acts as a metastasis suppressor, and loss of claudin-1 is positively correlated with poor outcomes in lung adenocarcinoma." (PMID 31024232, 2019). "Overexpression of CLDN1 suppresses the metastasis of lung adenocarcinoma 18, but the underlying mechanism remains unclear." (PMID 32754286, 2020). "Hence, we next explored whether the loss of CLDN1 induces the formation of CSCs or drug resistance via SLUG in lung adenocarcinoma." (PMID 32754286, 2020). "Recent reports have shown that Cldn1 is highly expressed in human lung adenocarcinoma-derived A549 cells and is involved in the augmentation of chemoresistance by the amino acid barrier." (PMID 40361399, 2025). "In lung adenocarcinoma, overexpression of CLDN1 has been shown to suppress migration and invasion of cancer cells (such as connective tissue growth factor, platelet reaction protein 1, etc.)." (PMID 40687428, 2025). "CLDN1 was shown to have an inhibitory effect on cancer metastasis in lung adenocarcinoma, as the upregulation of CLDN1 suppressed the ERK1/2 signaling pathway." (PMID 38731853, 2024). "The CLDN expression pattern of ACC–regarding CLDN1, -2, -3, -4, and -7—is most similar to that of lung adenocarcinoma with lepidic spread." (PMID 37621953, 2023). "CLDN1, as a downstream gene of NF-κB, promotes epithelial–mesenchymal transition of lung adenocarcinoma." (PMID 35813821, 2022). "In fact, CLDN1 expression induced by HDAC inhibitors in various low CLDN1-expressing lung adenocarcinoma cells increases their sensitivity to cisplatin." (PMID 36291810, 2022). "CLDN1 was also described as a potential predictive marker for chemotherapy response for lung adenocarcinoma." (PMID 36291810, 2022). "Lung adenocarcinoma patients with positive CLDN1 expression had poorer prognosis than negatives, and combination of CLDN1/Ras/EGFR was reported as a valuable independent prognostic factor." (PMID 33597819, 2021). "The low expression of CLDN1 in lung adenocarcinoma promoted the migration, invasion and metastasis of cancer cells, and was associated with a shorter OS." (PMID 34721537, 2021). "Lung adenocarcinoma data obtained from The Cancer Genome Atlas (TCGA) indicates that CLDN1 expression differs between tumor samples and normal samples." (PMID 32754286, 2020). "Because CLDN1 enhances the efficacy of chemotherapy, CLDN1 is not only a prognostic marker but a predictive marker for lung adenocarcinoma patients who are good candidates for chemotherapy." (PMID 32754286, 2020). "So far, we reported that the expression level of CLDN1 is increased by the acquisition of chemoresistance to CDDP in lung adenocarcinoma A549 cells." (PMID 32824620, 2020). "The mRNA level of CLDN1 was significantly increased in human lung adenocarcinoma and squamous cell carcinoma tissues compared to normal tissues, and has a tendency to increase in large cell and small cell tissues." (PMID 32824620, 2020). "For patients with lung adenocarcinoma, CLDN-1 is a potential drug treatment target and a useful predictor of prognosis." (PMID 31952355, 2020). "Both TCGA data and the GEO dataset show that CLDN1 is upregulated in stage I and II lung adenocarcinoma but downregulated in stage IV lung adenocarcinoma." (PMID 32754286, 2020). "Forced CLDN1 expression in low CLDN1-expressing lung adenocarcinoma will increase the chemotherapy response, providing a novel therapeutic strategy." (PMID 32754286, 2020). "In samples from patients with early-stage lung adenocarcinoma, CLDN1 expression was elevated compared with normal samples." (PMID 32754286, 2020).